HAGLROS (HAGLR opposite strand lncRNA)
Gene: Long non-coding RNA gene on chromosome 2 (176,177,717 to 176,179,018, forward strand). Ensembl gene ENSG00000226363.
Diseases named in the same sentence as HAGLROS in open-access papers:
HAGLROS is named in the same sentence as 16 diseases in open-access papers, as found by Europe PMC text mining. Sharing a sentence is not in itself a finding about the gene and the disease. The quoted sentences say what the papers report.
gastric cancer (8 papers, 2020 to 2023). A primary or metastatic malignant neoplasm involving the stomach. "HAGLROS, as a novel lncRNA, was first reported to promote the malignant phenotype of gastric cancer by sponging miR-100-5p to increase mTOR expression and interacting with mTORC1 components to activate the mTORC1 signalling pathway." (PMID 35664787, 2022). "For example, STAT3-induced the transcriptional activation of lncRNA lncRNA HAGLROS and strengthens the oncogenic potential of HAGLROS in gastric cancer." (PMID 32694944, 2020). "The overexpression of lncRNA HAGLROS has been found in gastric cancer and HCC and correlated with poor clinical outcomes in patients with these cancers." (PMID 33050642, 2020). "STAT3 promotes the increased expression of lncRNA HAGLROS, which leads to further progress of gastric cancer." (PMID 32831016, 2020). "Previous studies have shown that HAGLROS promotes the malignant progression of gastric cancer cells, suggesting that HAGLROS may be a malignant factor in cancer." (PMID 38112616, 2023). "In gastric cancer, HAGLROS was upregulated by the transcription factor STAT3." (PMID 33050642, 2020).
hepatocellular carcinoma (3 papers, 2022 to 2024). A malignant tumor that arises from hepatocytes. "For example, HAGLROS promotes proliferation, inhibits apoptosis and enhances autophagy by regulating the miR-5095/ATG12 axis and PI3K/AKT/mTOR signalling pathway in hepatocellular carcinoma." (PMID 35664787, 2022).
breast carcinoma (2 papers, 2021 to 2024). "Taken together, the upregulation of lncRNA HAGLROS was significantly associated with the poor prognosis of breast cancer patients." (PMID 39198393, 2024). "LncATLAS database and FISH results showed that lncRNA HAGLROS was mainly localized in the cytoplasm of breast cancer cells." (PMID 39198393, 2024). "In this study, we focused on the upregulated lncRNAs because of their possible use as therapeutic targets or prognostic biomarkers, among which lncRNA HAGLROS was one of the lncRNA significantly upregulated in breast cancer tissues." (PMID 39198393, 2024). "Endothelial tube formation and VM results showed that miR-135b-3p mimics restored the neovascularization and luminal structure formation abilities of HUVECs, HLECs and breast cancer cells promoted by lncRNA HAGLROS upregulation, and vice versa." (PMID 39198393, 2024). "Wound healing and Transwell results showed that miR-135b-3p mimics restored the migration and invasive ability of breast cancer cells promoted by lncRNA HAGLROS upregulation, and vice versa." (PMID 39198393, 2024). "Taken together, lncRNA HAGLROS is highly expressed in breast cancer and predicts poor patient prognosis, and promotes the biological behavior of breast cancer cells." (PMID 39198393, 2024). "To investigate the localization of lncRNA HAGLROS in breast cancer, we confirmed that lncRNA HAGLROS was mainly localized in the cytoplasm of breast cancer cells, with a small amount in the nucleus." (PMID 39198393, 2024). "UALCAN and lnCAR databases found that the expression of lncRNA HAGLROS in breast cancer tissues was significantly higher than that in adjacent normal tissues." (PMID 39198393, 2024). "In this study, we found that lncRNA HAGLROS was highly expressed in breast cancer tissues and plasma exosomes, and its high expression was related to the poor prognosis of breast cancer patients." (PMID 39198393, 2024). "A breast cancer lung metastasis model was constructed, in vivo fluorescence imaging and gross observation of lung tissue further confirmed that lncRNA HAGLROS overexpression significantly promoted lung metastatic ability, and vice versa." (PMID 39198393, 2024). "MTT, colony formation and EdU results showed that miR-135b-3p mimics restored the proliferative capacity of breast cancer cells promoted by lncRNA HAGLROS upregulation, and vice versa." (PMID 39198393, 2024). "ISH staining showed that lncRNA HAGLROS expression was upregulated in breast cancer tissues compared with the normal tissues and was mainly localized in the cytoplasm." (PMID 39198393, 2024). "To elucidate whether the interaction between lncRNA HAGLROS with miR-135b-3p can regulate the malignant evolution of breast cancer, we performed rescue experiments to examine the effect of miR-135b-3p in lncRNA HAGLROS differentially expressing cells." (PMID 39198393, 2024). "To determine the biological function of lncRNA HAGLROS in breast cancer cells, we examined lncRNA HAGLROS expression in breast cancer cells, and qRT-PCR results showed that the expression of lncRNA HAGLROS was significantly higher in breast cancer cell lines than in breast epithelial cells." (PMID 39198393, 2024). "Subsequently, we investigated the function of the lncRNA HAGLROS in breast cancer cell metastasis." (PMID 39198393, 2024). "Therefore, this study aimed to investigate the mechanism of lncRNA HAGLROS as ceRNA to regulate the malignant progression of breast cancer, reveal the regulatory mechanism of exosomal lncRNA HAGLROS between TAMs and breast cancer cells, and provide a potential target for breast cancer treatment." (PMID 39198393, 2024). "Our study confirmed that lncRNA HAGLROS regulates the proliferation, migration, invasion, EMT process and angiogenesis ability of breast cancer cells through miR-135b-3p." (PMID 39198393, 2024).
breast carcinoma (continued). "We further selected five lncRNAs (DSCR8, TP53TG1, CBR3-AS1, LINC01006, HAGLROS) that were not previously reported to be related to the drug sensitivity of breast cancer and performed qRT-PCR to verify their expression levels." (PMID 33494806, 2021).
intrahepatic cholangiocarcinoma (2 papers, 2022 to 2024). A carcinoma that arises from the intrahepatic bile duct epithelium in any site of the intrahepatic biliary tree. "Notably, recent study indicated that HAGLROS was highly expressed and decreasing HAGLROS can inactivate the mTOR axis and elevate autophagy through improving lipid metabolism reprogramming in intrahepatic cholangiocarcinoma." (PMID 35664787, 2022).
lymph node metastasis (2 papers, 2018 to 2024). "Furthermore, the clinicopathological analysis revealed that the expression level of lncRNA HAGLROS was positively correlated with lymph node metastasis (P = 0.021), distant metastasis (P = 0.002), TNM stage (P = 0.000) and ER (P = 0.038) expression of patients." (PMID 39198393, 2024). "Multivariate analysis further revealed that HAGLROS expression could be regarded as a potential diagnostic biomarker for overall survival in patients with GC (P = 0.005), for TNM stage (P = 0.019) and for lymph node metastasis (P = 0.001)." (PMID 29329543, 2018).
Nephroblastoma (2 papers, 2022 to 2024). An embryonal neoplasm characterized by the presence of epithelial, mesenchymal, and blastema components. "In summary, our findings revealed that HAGLROS expression might be associated with pathogenesis of nephroblastoma." (PMID 35358010, 2022). "In summary, our results revealed that HAGLROS executed an oncogenic role in the progress of nephroblastoma, offering a new perspective on the strategy for nephroblastoma therapy." (PMID 35358010, 2022). "Consistently, our study revealed that HAGLROS expression was increased in nephroblastoma cells, among which HFWT cells showed the highest HAGLROS level." (PMID 35358010, 2022). "In addition, we will explore the expression pattern of HAGLROS in nephroblastoma by bioinformatics analysis in further study." (PMID 35358010, 2022). "However, the biological role of HAGLROS in the occurrence and progression of nephroblastoma remains incompletely discovered." (PMID 35358010, 2022). "In addition, we found that the proliferation, migration and invasion of HFWT cells were inhibited after downregulation of HAGLROS, suggesting the oncogenic role of HAGLROS in nephroblastoma." (PMID 35358010, 2022). "Thus, we plan to explore roles of HAGLROS in other nephroblastoma cell lines to verify our results and perform animal and clinical trials about HAGLROS in the further experiments." (PMID 35358010, 2022). "The data indicate that HAGLROS plays a regulatory role in cell apoptosis of nephroblastoma." (PMID 35358010, 2022). "HAGLROS may regulate nephroblastoma cell apoptosis via mediating the activation of autophagy." (PMID 35358010, 2022). "Thus, HAGLROS may be involved in nephroblastoma cell autophagy." (PMID 35358010, 2022).
ovarian carcinoma (2 papers, 2024 to 2025). A malignant neoplasm originating from the surface ovarian epithelium. "HAGLROS is an upregulated lncRNA in ovarian cancer cells; HAGLROS knockdown increases apoptosis rate, upregulates BAX protein expression, and downregulates BCL-2 protein expression via the HAGLROS/miR-26b-5p axis (Zhu and Mei, 2021)." (PMID 39967908, 2025).
cervical cancer (1 paper, 2025). A primary or metastatic malignant neoplasm involving the cervix. "The results of GEPIA database showed that CDKN2B-AS1, MIR205HG, and HAGLROS were highly expressed in cervical cancer, and patients with high expression levels had poorer prognoses." (PMID 40822023, 2025). "The results showed that CDKN2B-AS1, MIR205HG, and HAGLROS were highly expressed in cervical cancer, whereas GATA6-AS1 and DICER1-AS1 showed low expression levels in cervical cancer." (PMID 40822023, 2025). "The prognostic significance of CDKN2B-AS1, MIR205HG, HAGLROS, GATA6-AS1, and DICER1-AS1 in cervical cancer patients was evaluated by using the KM-Plotter database." (PMID 40822023, 2025).
cervical squamous cell carcinoma (1 paper, 2022). A squamous cell carcinoma arising from the cervical epithelium. "HAGLROS expression in common tumours was analysed using the GEPIA database, and the results showed that HAGLROS was highly expressed in most tumours, including BC, lung squamous cell carcinoma, and cervical squamous cell carcinoma." (PMID 35664787, 2022).
colorectal cancer (1 paper, 2020). A primary or metastatic malignant neoplasm that affects the colon or rectum. "In colorectal cancer cells, HAGLROS (HOXD antisense growth-associated lncRNA) regulates apoptosis and autophagy to resist cell death; the PI3K/AKT/mTOR pathway and ATG5, a biomarker of autophagy, are the possible functional targets of HAGLROS." (PMID 32928281, 2020).
nasopharyngeal carcinoma (1 paper, 2025). A carcinoma arising from the nasopharyngeal epithelium. "Previous studies have shown, upregulation of lncRNA HAGLROS enhances nasopharyngeal carcinoma development by modulating PI3K/AKT/mTOR signaling mediated by miR-100/ATG14 axis." (PMID 40756984, 2025).
cancer (8 papers, 2017 to 2025). A tumor composed of atypical neoplastic, often pleomorphic cells that invade other tissues. "Subsequently, accumulating evidence has shown that HAGLROS is closely associated with proliferation, invasion, autophagy and drug resistance, and plays a vital role in the occurrence and progression of various cancers." (PMID 35664787, 2022). "In our research, a few of the DEirlncRNAs in the model have already been revealed to play roles in various cancers, such as HAGLROS, LBX2-AS1, LINC00900, LINC01614, AC090673.1, and especially TC, while others were found to be related to TC for the first time." (PMID 35996170, 2022). "In brief, growing evidence indicates that HAGLROS is closely related to apoptosis, autophagy, drug resistance and metabolic reprogramming and plays an oncogenic role in most cancers." (PMID 35664787, 2022). "Upregulation of HAGLROS, PVT1, LINC00160, NEAT1, HCG11, and MCM3AP-AS in cancers were associated with poor clinical outcomes in patients with HCC." (PMID 33050642, 2020). "HAGLROS, one of the lncRNAs, has been reported to be abnormally expressed in many types of malignancies, presenting a carcinogenic role and contributing to the malignant processes of a number of cancers." (PMID 35358010, 2022). "HAGLROS was also found to affect proliferation, migration and invasion in other types of cancers." (PMID 35358010, 2022). "LncRNAs such as CDKN2B-AS1, MIR205HG, HAGLROS, GATA6-AS1 and DICER1-AS1 are related to cancer research." (PMID 40822023, 2025). "In addition, CTD‐2008L17.2, HAGLROS, AC093609.1, UNC5B‐AS1, and RUNDC3A‐AS1 were shown to play vital roles in determining the histological cancer type." (PMID 31044550, 2019). "Nevertheless, the key role of HAGLROS in other cancer like PTC has not been reported." (PMID 38112616, 2023). "However, there was no further evidence to indicate whether HAGLROS affected the cancer directly or was only passenger of other cancer-related genes." (PMID 28496001, 2017).
tumor (5 papers, 2018 to 2024). "Studies have reported that lncRNA HAGLROS act as ceRNA to regulate miRNA, thereby inhibiting the translation or degradation of target genes and promoting tumor progression." (PMID 39198393, 2024). "In the present study, we found that the lncRNA HAGLROS was significantly overexpressed in GC compared to corresponding non-tumor tissues." (PMID 29329543, 2018). "In this study, we aim to examine the expression pattern of lncRNA HAGLROS in GC and its clinical significance as well as its biological role in tumor progression." (PMID 29329543, 2018). "The lncRNA HAGLROS is highly expressed in CRC and associated with decrease in OS in tumor patients." (PMID 33850225, 2021). "HAGLROS levels were also correlated with tumor invasion depth and TNM stage." (PMID 29329543, 2018). "Therefore, up-regulation of HAGLROS in GC is partly due to STAT3 activation during tumor progression." (PMID 29329543, 2018).
HAGLROS also shares sentences with these, for which no sentence is quoted: lung carcinoma (1 paper); lung squamous cell carcinoma (1); osteosarcoma (1).